GLO1 (glyoxalase I)
Diseases named in the same sentence as GLO1 in open-access papers (continued):
Sharing a sentence is not in itself a finding about the gene and the disease.
tumor (continued). "Primary or adjunct chemotherapy with Glo1 inhibitor to counter Glo1-mediated MDR may improve treatment outcomes and high Glo1 expression may be a biomarker of likely tumor susceptibility to Glo1 inhibitor therapy." (PMID 35269594, 2022). "Having discovered the spliceosome as a target of MG-induced toxicity, we assessed if expression of Glo1 may be linked to protection of the spliceosome in human tumor cell lines and clinical human tumors." (PMID 34790575, 2021). "The association of Glo1 with tumor growth could suggest its role as an oncogene, but this seems to be more an adaption to protect the tumor proteome against an increased intracellular flux of MG formation." (PMID 33019494, 2020). "Increased GLO1 copy-number is associated with multidrug resistance in tumour chemotherapy, but prevalence of GLO1 CNV in gastro-entero-pancreatic neuroendocrine tumours (GEP-NET) is unknown." (PMID 29100361, 2017). "This may be due to GLO1 allele deletion or tumour genetic instability; or DNA damage in sample processing, thereby disrupting binding of primers for qPCR." (PMID 29100361, 2017). "Moreover, increased GLO1 copy number was associated with a significantly shorter time to tumour progression in patients with midgut NET." (PMID 29100361, 2017). "To evaluate whether the loss of GLO1 in CRC cells had an impact on tumor growth in vivo, we set-up a silencing strategy in HCT116 cells." (PMID 28117708, 2017). "MDR tumours are susceptible to cell permeable Glo-1 inhibitors." (PMID 27406712, 2016). "Cell permeable Glo-1 inhibitors which increase dicarbonyl stress may find use as anti-tumour and anti-microbial agents for treatment of Glo-1-linked MDR tumours and microbial infections." (PMID 27406712, 2016). "The clinical outcome of novel GLO-1 inhibitors will likely depend on tumor type, expression levels, immune infiltration, and treatment context." (PMID 40727469, 2025). "The hypoxic conditions often present within tumor microenvironments further potentiate GLO-1 activity, thereby exacerbating this resistance mechanism." (PMID 40727469, 2025). "Overall, the more oxidized state of GLO1 together with lower sLG levels suggests a potentially reduced ability of tumor cells to metabolize MG or perhaps less need for the cells to metabolize it." (PMID 40461450, 2025). "Future work should focus on identifying and optimizing small-molecule GLO-1 inhibitors that exploit tumor metabolic dependency on glyoxalase detoxification." (PMID 40727469, 2025). "Using TIMER, we identified significant correlations between GLO-1 expression and immune infiltration in 19 of the 35 analyzed tumor types." (PMID 40727469, 2025). "GLO-1 expression also showed a positive correlation with TMB in several tumor types, including LUAD, UCEC, LIHC, MESO, STAD, SKCM, and READ." (PMID 40727469, 2025). "In tumor cells exhibiting high rates of aerobic glycolysis, increased expression of GLO-1 appears to be a crucial adaptation, enhancing the detoxification of MG and contributing to resistance against multiple therapeutic agents." (PMID 40727469, 2025). "Silencing Glo1 inhibits tumor growth and induces apoptosis, suggesting its potential as a therapeutic target and prognostic indicator." (PMID 38398772, 2024). "As more than 50% of tumor treatment drugs originate from natural compounds, the exploration of bioactive compounds like resveratrol, curcumin, and piperine as Glo1 inhibitors opens avenues for novel therapeutic interventions." (PMID 38785990, 2024). "GLO1 has been shown in several preclinical models to promote tumor cell proliferation, and one study showed GLO1 upregulating PD-L1 expression, suggesting positive treatment response when it is targeted." (PMID 37671166, 2023). "The results showed that GLO1 protein expression was down-regulated in tumor tissues with high miR-205-3p expression." (PMID 37814205, 2023).
tumor (continued). "Consistent DNA hypermethylation was observed in tumor xenografts generated by implantation of GLO1-depleted cells in NOD-SCID mice." (PMID 36998085, 2023). "More specifically, we have shown a trend toward the detection of higher levels of HSP27, MG adducts, and GLO1 in gemcitabine-treated versus untreated PDAC tumor samples using immunohistochemistry." (PMID 37408249, 2023). "Even so, BBGD had antitumor activity in tumor-bearing mice and was particularly effective against tumors with high Glo1 expression and resistance to established anticancer drugs." (PMID 35269594, 2022). "In colon cancer, the silence of GLO1 can also inhibit these tumor properties via up-regulating the transcription-1 (STAT1) expression and the B-cell lymphoma-2 (Bcl-2)/Bcl-2-associated X protein (Bax)—mediated apoptosis signal." (PMID 36612084, 2022). "The DNA segment copied in tumor GLO1 copy number increase was larger than in gene duplication in the healthy population." (PMID 35269594, 2022). "Twofold and higher amplification of GLO1 in tumor tissues is identified in the breast, sarcomas, NSCLC, bladder, renal, and gastric cancers." (PMID 36612084, 2022). "The glyoxalase system comprises glyoxalase 1 (Glo1) and glyoxalase 2 (Glo2), which is often overexpressed in various tumor tissues." (PMID 35898868, 2022). "It has been reported that The high levels of MG which are produced due to high glycolytic activity, controlled by increased Glo-1 expression and activity in several tumor cells." (PMID 35223406, 2021). "Here, we have evaluated GLO1 expression by immunohistochemistry in tumor samples from a PCa patient cohort." (PMID 34298821, 2021). "In previous studies, it has been shown that inhibition of Glo1 in tumor cells in vitro leads to the accumulation of MG, increasing protein and DNA modification and apoptosis." (PMID 34790575, 2021). "Here, we have evaluated GLO1 expression by immunohistochemistry in archival tumor samples from 187 PCa patients (stage 2 and 3)." (PMID 34298821, 2021). "Immunohistochemical analysis revealed GLO1 upregulation during tumor progression, observable in HGPIN and PCa versus normal prostatic tissue." (PMID 34298821, 2021). "This indicates that there was a similar correlation of Glo1 expression in human clinical tumors as in the human tumor cell lines of the CCLE." (PMID 34790575, 2021). "These evidence suggest a prognostic role for Glo1 tumor expression, as further indicated in fibrosarcoma progression by a proteomic analysis." (PMID 33869040, 2021). "We also observed a consistent increase of GLO1 activity in the tumor parallel with pair-matched normal tissue." (PMID 35223406, 2021). "Of note, 9 (75%) of the patients who died from PCa showed a high expression of Glo1, highlighting a trend of worse outcomes for the neoplasms expressing high levels of this protein (p = 0.094)." (PMID 34199263, 2021). "Glyoxalase 1 (GLO1) is an enzyme involved in energy metabolism in various tumor types including PCa." (PMID 34298821, 2021). "AP-2α, E2F4, and Nrf2 are some of the regulators of Glo1 and are highly expressed in tumor cells, and thus induce Glo1 overexpression." (PMID 33396745, 2020). "Glo1 overexpression protects tumor cells against cytotoxicity induced by anti-tumor drugs, whereas inhibition of Glo1 expression overcomes multidrug resistance and restores tumor sensitivity to anti-tumor drugs." (PMID 33396745, 2020). "The overexpression of Glo1 in tumor cells makes this enzyme a pivotal target for anticancer drug development, and, in fact, Glo1 inhibitors, alone or in combination with other drugs, have offered potential benefit in the management of some human malignancies." (PMID 31174324, 2019). "In this study, GLO1 silencing favored a pro-migratory and metastatic phenotype, suggesting a tumor-suppressing role of GLO1." (PMID 30674353, 2019). "The formation of S-lactoyl glutathione is catalysed by glyoxalase 1 (Glo1) and under-expression can promote tumour growth." (PMID 30866469, 2019).
tumor (continued). "We also demonstrated that the accumulation of MG-H1 in ATC tumors was consequent to a decreased functionality of Glo1, the major enzymatic defense against MG-mediated glycation, thus suggesting a tumor-suppressing role for this protein in ATC." (PMID 31174324, 2019). "We confirm that methylglyoxal is a byproduct of glucose metabolism in NSCLC and additionally show that Glo1 expression supports tumor growth in mice." (PMID 31811141, 2019). "Perhaps counter-intuitively, over expression of Glo1 is a biomarker for tumour growth, but this is likely to reflect high-glycolytic activity, as we observed in SCC tissues." (PMID 30866469, 2019). "On the other hand, Glo1 expression correlated with Neoplasm histologic grade in the METABRIC dataset (χ2 test, p = 0.002)." (PMID 30559934, 2018). "Because we showed that high Glo1 expression correlates with tumor grade and grade 3 tumors, Kaplan-Meier analysis taking into consideration Glo1 expression and neoplasm histologic grade was performed using the METABRIC dataset." (PMID 30559934, 2018). "Here, we uncover a novel mechanism linking Glo1 to the maintenance of the metastatic phenotype of PCa cells by controlling EMT by engaging the tumour suppressor miR‐101, MG‐H1‐AP and TGF‐β1/Smad signalling." (PMID 29504694, 2018). "GLO1 inhibition using TLSC702 suppressed ALDH1high cell viability as well as the formation of tumor-spheres by ALDH1high cells." (PMID 30559934, 2018). "We consistently detected a high level of MG adducts and low GLO1 activity in high stage tumors compared to low stage ones suggesting a pro-tumor role for dicarbonyl stress." (PMID 28117708, 2017). "For midgut NET, there were 4 tumours with unchanged GLO1 copy number, 3 tumours had decreased GLO1 copy number and 18 with increased GLO1 copy number (P<0.01)." (PMID 29100361, 2017). "To assess the consequence of GLO1 inhibition on tumor cell survival we cultured both cell lines in the presence of the cell permeable inhibitor S-p-bromobenzylglutathione cyclopentyl diester." (PMID 28549423, 2017). "In the pre-malignant state, Glo1 is a tumour suppressor protein, which is likely mediated through suppression of MG modifications of DNA and associated mutagenesis." (PMID 29100361, 2017). "GLO1 is a central part of a ubiquitous detoxification system in the glycolytic pathway of normal and tumor cells, and enables cell proliferation and survival under dicarbonyl stress." (PMID 28549423, 2017). "The data presented so far suggested that induced GLO1 expression is a compensatory mechanism of OPSCC tumor cells to counteract and survive the accumulation of MG." (PMID 28549423, 2017). "Accordingly, GLO1 overexpression was found in several human malignancies, and is also a common feature in tumor tissue of primary OPSCC as demonstrated by immunohistochemistry in this study." (PMID 28549423, 2017). "A heterogeneous staining pattern was also evident for GLO1 considering the staining intensity as well as the relative amount of positive tumor cells." (PMID 28549423, 2017). "Accordingly, GLO1 depletion in CRC cells promoted tumor growth in vivo that was efficiently reversed using carnosine, a potent MG scavenger." (PMID 28117708, 2017). "It is worth noting that in addition to the expected positive staining in the cytoplasm of tumor cells, we also detected a prominent nuclear GLO1 staining in a substantial amount of OPSCC samples." (PMID 28549423, 2017). "Increased GLO1 copy number appeared to be clinically functional through link to increased tumour progression in midgut NET." (PMID 29100361, 2017). "In a substantial amount of OPSCCs with GLO1 expression, we detected a predominant nuclear staining in tumor cells." (PMID 28549423, 2017). "Previous experimental studies suggest that tumour cell lines with high GLO1 copy number and Glo1 expression have high glycolytic rate, high flux of MG formation and relatively high content of DNA glycation adducts." (PMID 29100361, 2017).
tumor (continued). "Comparable GLO1 copy number in metastatic and primary tumour indicated that increased GLO1 copy number, once acquired by the GEP-NET, was maintained." (PMID 29100361, 2017). "It seems plausible to assume that highly proliferative cells like tumor cells possess a higher glycolytic flux that makes them more prone to inhibition of GLO1 and PK." (PMID 27579985, 2016). "Grafted GLO1-depleted cells on the CAM showed increased growth as assessed by the measure of tumor volume and compared to control cells." (PMID 27759563, 2016). "After 6 weeks post-tumor removal, metastasized tumors were observed in the lungs of GLO1-depleted mice (68%) when compared to control (20%)." (PMID 27759563, 2016). "Altogether, we conclude that GLO1 on one hand is crucial to maintaining tumor characteristics of malignant cells, and, on the other hand, supports malignant transformation of cells in a hypoxic environment when overexpressed." (PMID 27999356, 2016). "These are likely tumours with a relatively high flux of MG formation and high activity of Glo-1 such that when a Glo-1 inhibitor is delivered into the tumour, MG accumulates rapidly to toxic levels." (PMID 27406712, 2016). "In the present study, we show that knockdown of GLO1 in MCF-7 tumor cells significantly reduced the malignant properties of the cells, characterized by the reduction of cell proliferation, cell migration and anchorage-independent growth." (PMID 27999356, 2016). "The specific activity of the GLO1 in PBMC was found to be approximately 6 times lower compared to tumor cells." (PMID 27579985, 2016). "Stably GLO1-depleted MDA-MB-231 cells that were grafted subcutaneously in mice showed an increased tumor weight and volume that reached significance for shGLO1#2-silenced clones." (PMID 27759563, 2016). "Most of the recent studies aimed at the inhibition of GLO1 to induce a toxic MG accumulation effectively showed a decreased tumor growth." (PMID 27759563, 2016). "We found that PK was the only enzyme whose activity was significantly reduced as a consequence of GLO1-knockdown in MCF-7 tumor cells." (PMID 27999356, 2016). "To assess the impact of GLO1 expression on different tumor cell parameters, we compared the doubling time of cells, cell migration and proliferation to wild type and mock-transfected cells." (PMID 27999356, 2016). "Increased Glo1 expression in particular was described as being related to glycolytic activity in many tumor types." (PMID 24958267, 2013). "We found higher Glo1 and LDH activity to be associated with enhanced glycolytic activity and cell migration and, therefore, with tumor aggressiveness." (PMID 24958267, 2013). "Our results confirmed a significant increase in GLO1 expression in tumor tissues (P = 0.005, one-sample Kolmogorov-Smirnov test)." (PMID 22479608, 2012). "That is most tumor cells, such as cells derived from prostate, breast, and colon cancer, displayed increased expression of Glo1 in conjunction with enhanced anaerobic breakdown of glucose to lactate." (PMID 20454679, 2010). "In addition, we found that the risk of BC associated with the GLO1 E allele significantly tended to increase according to tumour stage, thus suggesting a possible role of this polymorphism, not only in the development of this neoplasia but also in progression of local to advanced BC." (PMID 19379515, 2009). "The specific activity of Glo1 in mononuclear blood cells was approximately 1/10 compared to tumor cells (unpublished data)." (PMID 18946510, 2008). "Curcumin decreased D-lactate release by tumor cells, another clue for inhibition of intracellular Glo1." (PMID 18946510, 2008). "The results demonstrated between 10- and 70-fold decrease in specific activity of Glo2 compared to Glo1 in different tumor cell lines." (PMID 18946510, 2008).
tumor (continued). "This can be explained by the different expression of Glo1 in mononuclear blood cells compared to tumor cells." (PMID 18946510, 2008). "GLO-1 was significantly downregulated in KIRP (Tumor: 5.58 ± 0.68, Normal: 6.07 ± 1.49, p = 3.2e−21), KIPAN (Tumor: 5.74 ± 0.67, Normal: 6.07 ± 1.49, p = 3.0e−18), KIRC (Tumor: 5.86 ± 0.63, Normal: 6.07 ± 1.49, p = 5.5e−12), and KICH (Tumor: 5.54 ± 0.70, Normal: 6.07 ± 1.49, p = 4.2e−10)." (PMID 40727469, 2025). "The tumor-specific variability in GLO1 methylation may also explain differences in clinical outcome, such as immune evasion or therapeutic response." (PMID 40727469, 2025). "The observation that low GLO1 expression in human PDAC tumor tissue correlates with increased sensitivity to IKE suggests that assessing GLO1 expression may help identify patients suitable for ferroptosis‐targeted therapy." (PMID 40908564, 2025). "Similarly, GLO1 knockout potentiated the antitumor effect of IKE in both PANC1 and HCT116 xenografts, further supporting the role of GLO1 in ferroptosis resistance and tumor progression." (PMID 40908564, 2025). "GLO-1 levels were associated with immunotherapy markers like microsatellite instability (MSI) and tumor mutational burden (TMB), with positive correlations between GLO-1 and MSI in UCEC, TGCT, and STAD, and between GLO-1 and TMB in LUAD, UCEC, LIHC, MESO, SKCM, and READ." (PMID 40727469, 2025). "Indeed, GLO-1 appears to function as a dual mediator, exhibiting both oncogenic and tumor-suppressive activities." (PMID 40727469, 2025). "As one key property which distinguishes tumor to normal tissue is hypoxia, we wondered if hypoxia itself might play a role in inhibition of the glyoxalase pathway as hypoxia-driven GLO1 deactivation was suggested already by previous studies." (PMID 40461450, 2025). "This analysis further revealed a complex interplay between GLO-1 and the tumor immune landscape." (PMID 40727469, 2025). "Specifically, GLO-1 inhibition could potentially enhance the effectiveness of immunotherapy by creating a more favorable tumor microenvironment conducive to immune cell infiltration and cytotoxic activity." (PMID 40727469, 2025). "At the same time, the expression of GLO1 showed variability in different types of the same tumor." (PMID 40352588, 2025). "In fact, Glo1 has been identified as an important contributing factor to the progression of this neoplasia, frequently through the major AGE formed by the non-enzymatic reaction of MG with arginine residues of proteins, MG-H1, and also with the involvement of the receptor for AGEs, RAGE." (PMID 41009024, 2025). "Moreover, Glo-1 and Glo-2 measurement in tumors, as well as by any tumor immuno-histochemical analysis, cannot be used repeatedly for the follow-up of patients." (PMID 39682111, 2024). "GLO1 is present in all tissue, together with glyoxalase 2 and the cofactor glutathione, forms the glyoxalase system, the major detoxification enzyme system for carboxaldehyde, with increased expression reported in several tumours." (PMID 37814205, 2023). "In experimental studies of liver carcinogenesis, in the non-malignant state, Glo1 was identified as a tumor suppressor protein —likely linked to some targets of MG glycation facilitating malignant transformation." (PMID 35269594, 2022). "Increased expression of Glo1 may provide a protective shield of the spliceosome against MG glycation permissive for tumor growth." (PMID 34790575, 2021). "This suggests that the efficacy of anti-tumor strategies involving the use of BrBzGSHCp2 can be ascribed to differences in cell lines and animal models used and, in general, is more efficient in a neoplastic context where Glo1 is expressed at high levels." (PMID 33869040, 2021). "GLO1 activity and expression is generally increased in many tumor cells." (PMID 34440621, 2021).